B3GAT1 (beta-1,3-glucuronyltransferase 1)
Description:
Involved in the biosynthesis of L2/HNK-1 carbohydrate epitope on glycoproteins. Can also play a role in glycosaminoglycan biosynthesis. Substrates include asialo-orosomucoid (ASOR), asialo-fetuin, and asialo-neural cell adhesion molecule. Requires sphingomyelin for activity: stearoyl-sphingomyelin was the most effective, followed by palmitoyl-sphingomyelin and lignoceroyl-sphingomyelin. Activity was demonstrated only for sphingomyelin with a saturated fatty acid and not for that with an unsaturated fatty acid, regardless of the length of the acyl group.
Synonyms: GlcAT-P; GLCATP; CD57; GLCUATP; HNK1; LEU7; NK-1; NK1
Tractability: Small molecule: a structure with a bound ligand is known; it has a binding pocket of medium quality. Antibody: UniProt places it where antibodies can reach, with medium confidence; UniProt predicts a signal peptide or a membrane-spanning region; its Gene Ontology location is reachable by antibodies, with medium confidence.
Gene: Protein-coding gene on chromosome 11 (134,378,504 to 134,412,242, reverse strand). Ensembl gene ENSG00000109956.
Subcellular location: Golgi apparatus membrane (Isoform 1); Secreted; Golgi apparatus membrane (Isoform 2); Endoplasmic reticulum membrane
Subcellular location (Human Protein Atlas): Vesicles; Predicted to be secreted
Pathways (Reactome):
Metabolism: Glycosaminoglycan-protein linkage region biosynthesis
Gene Ontology:
Molecular function: protein binding; galactosylgalactosylxylosylprotein 3-beta-glucuronosyltransferase activity
Biological process: carbohydrate metabolic process; chondroitin sulfate proteoglycan biosynthetic process; glycosaminoglycan biosynthetic process
Cellular component: endoplasmic reticulum membrane; Golgi membrane; membrane; extracellular region
Genetic constraint (gnomAD): Loss-of-function variants: 11 observed, 24.3 expected, observed/expected ratio (o/e) 0.45, 90% interval 0.28 to 0.75. The synonymous counts are far from expectation, so gnomAD's model fits this gene poorly and the ratio says little. Missense variants: 375 observed, 438.02 expected, observed/expected ratio (o/e) 0.86, 90% interval 0.79 to 0.93. Synonymous variants: 255 observed, 201.66 expected, observed/expected ratio (o/e) 1.26, 90% interval 1.14 to 1.4.
Homologues: Orthologues: chimpanzee B3GAT1 (99% identical), macaque B3GAT1 (99% identical), mouse B3gat1 (99% identical), rat B3gat1 (99% identical), pig B3GAT1 (98% identical), rabbit B3GAT1 (98% identical), guinea pig B3GAT1 (97% identical), dog B3GAT1 (97% identical), tropical clawed frog b3gat1 (86% identical), zebrafish b3gat1a (86% identical), zebrafish B3GAT1 (68% identical), Caenorhabditis elegans glct-1 (34% identical), and 5 more. Paralogues in human: B3GAT2 (49% identical), B3GAT3 (48% identical).
Diseases named in the same sentence as B3GAT1 in open-access papers:
B3GAT1 is named in the same sentence as 271 diseases in open-access papers, as found by Europe PMC text mining. Sharing a sentence is not in itself a finding about the gene and the disease. The quoted sentences say what the papers report.
viral infections (44 papers, 2007 to 2026). "Further, EV-D68 infection of B3GAT1-expressing cells resulted in a ~100-fold reduction in viral infection as determined by TCID50." (PMID 36309510, 2022). "Since B3GAT1 overexpression induced strong and broad protection from viral infection, we next wanted to evaluate the potential of B3GAT1 expression as an antiviral strategy." (PMID 36309510, 2022). "For example, future studies will be needed to determine the minimal proportion of cells in the respiratory tract that need to express B3GAT1 to confer protection against viral infection." (PMID 36309510, 2022).
influenza (14 papers, 2011 to 2023). An acute viral infection of the respiratory tract, occurring in isolated cases, in epidemics, or in pandemics; it is caused by serologically different strains of viruses (influenzaviruses) designated A, B, and C, has a 3-day incubation period, and usually lasts for 3 to 10 days. "As B3GAT1 overexpression had provided protection in all tested cell culturing systems, we next wanted to determine if we could utilize this strategy to protect from influenza disease progression in vivo." (PMID 36309510, 2022). "Upon observing that B3GAT1 expression reduces surface sialic acid expression, we hypothesized that the binding of influenza virions to host cells would be impaired and that lack of receptor binding was ultimately responsible for the inhibition of infection." (PMID 36309510, 2022).
prostate carcinoma (9 papers, 2011 to 2023). A carcinoma that arises from epithelial cells of the prostate gland. "This eQTL is predicted to be specific to NK cells, and colocalises with a GWAS63 risk locus for prostate cancer (PP4 = 0.949), with decreased NK cell B3GAT1 expression being associated with increased prostate cancer risk." (PMID 35835762, 2022). "Furthermore, data query showed that LuCaP 49 was CD57+ (B3GAT1; a marker associated with cells showing neuroendocrine differentiation), CD44-, CD107b+ (LAMP2, expressed by many prostate cancer cell types), CD10-, CD133+; LuCaP 35 was CD57-, CD44-, CD107b+, CD10+, CD133-." (PMID 21605402, 2011). "B3GAT1, also known as CD57, expression was previously tested in 3672 prostate cancer and benign specimens by IHC." (PMID 32252688, 2020).
schizophrenia (4 papers, 2010 to 2020). A major psychotic disorder characterized by abnormalities in the perception or expression of reality. "B3GAT1 has also been implicated in major psychiatric disorders, as schizophrenia and schizoaffective disorders." (PMID 33187165, 2020). "Human GlcAT-P (B3GAT1) has been implicated as a candidate gene for schizophrenia-like psychosis and b3gat1 knock-out mice have been reported to have synaptic plasticity defects." (PMID 22132223, 2011). "Knockout mice for the B3GAT1 orthologous gene exhibit impaired synaptic plasticity and spatial learning, 2 abnormalities also described in patients with schizophrenia." (PMID 20967226, 2010).
anaphylaxis (2 papers, 2016 to 2025). An acute hypersensitivity reaction that occurs from exposure to an allergen. "ISM patients with insect venom–induced anaphylaxis show distinct gene expression profiles compared to those without such reactions, while significant expression of TRAF4 is linked to food hypersensitivity and reduced B3GAT1 expression is associated with insect venom‐triggered anaphylaxis." (PMID 41031827, 2025). "B3GAT1 gene was underexpressed in patients with anaphylaxis." (PMID 27086366, 2016).
psychosis (2 papers, 2011 to 2014). "B3GAT1 is near a balanced translocation that segregates in a family with psychosis and depression, and an association to B3GAT2 has been found in SZ." (PMID 24736721, 2014).
allergies (1 paper, 2021). "Furthermore, allergies to insect venom are associated with the expression of B3GAT1 gene (that encodes the enzyme 3-beta-glucuronosyltransferase 1, and its enzymatic activity creates the CD57 epitope on other cell surface proteins)." (PMID 33918305, 2021).
colitis (1 paper, 2008). Inflammation of the colon. "Thus, TNBS colitis was characterized by an absence of significant changes in markers of T cells (Thy1, Tcrb, Tcrg, Zap70, Lck), B cells (Ptprc -B220-, Ms4a1 -Cd20-, Cd22, Cd79b) and NK cells (Baat, Ncam1 -Cd56-, B3gat1 -Cd57-)." (PMID 18928539, 2008).
invasive breast carcinoma (1 paper, 2021). A carcinoma that infiltrates the breast parenchyma. "In this work, we observed that higher expression of the signature genes CD4, KLRG-1, and B3GAT1 correlated with a higher survival rate when we analyzed the OS of patients from two invasive breast carcinoma cohorts from the TCGA consortium." (PMID 34386013, 2021).
mastocytosis (1 paper, 2016). A clonal myeloproliferative neoplasm characterized by the proliferation and accumulation of neoplastic mast cells in one or multiple organs or organ systems. "The TRAF4 expression was higher in mastocytosis patients with food hypersensitivity in their medical history, the B3GAT1 expression was lower in mastocytosis patients with IVA in history." (PMID 27086366, 2016). "The results of the study indicate the increased expression of TRAF4 in mastocytosis patients with food hypersensitivity and decreased expression of B3GAT1 in mastocytosis patients with IVA." (PMID 27086366, 2016).
tumor (201 papers, 1985 to 2026). "Our data demonstrated that GPX8 was correlated with mRNA expression of immune markers of CD8+ T cells (CD8B), CD4+ T cells (CD4), T cells (CD3D), macrophages (CD68 and ARG1), neutrophils (ITGAM and CCR7), dendritic cells (NRP1), NK cells (B3GAT1), and tumor-associated fibroblasts (FAP)." (PMID 36061208, 2022). "Meanwhile, GPX8 mRNA expression was significantly correlated with monocyte marker CD14, dendritic-cell marker NRP1, natural killer cell marker B3GAT1, neutrophil marker CCR7, and tumor-associated fibroblast marker FAP." (PMID 36061208, 2022). "To confirm that our findings would translate beyond cancerous cell culture lines, we overexpressed B3GAT1 in NL20 cells, which are non-tumor human lung cells, and again observed suppression of infection with IBV." (PMID 36309510, 2022). "B3GAT1 gene and antigen CD57 play an important role in immune system and neoplasm processes." (PMID 27086366, 2016).
infection (77 papers, 2007 to 2025). The state of being infected such as from the introduction of a foreign agent such as serum, vaccine, antigenic substance or organism. "We found that while both viruses caused severe, lethal disease in our GFP-transduced control mice, mice transduced with B3GAT1 displayed only minimal bodyweight loss after infection and 100% of the animals survived the challenge." (PMID 36309510, 2022). "To test this, we infected cells across a range of multiplicities of infection (MOIs) and found that while higher MOIs resulted in more total B3GAT1 cells infected, B3GAT1 still restricted infection with respect to control at all MOIs tested." (PMID 36309510, 2022). "Our data show that infection with IBVs and IAVs is significantly hindered by B3GAT1 both in vitro and in vivo, and that viral restriction occurred irrespective of when the virus was isolated or the specifics of its receptor preferences." (PMID 36309510, 2022). "B3GAT1 overexpression in these AAV-transduced ALI cultures reduced the infection and productive titer of both the IBV strain B/Malaysia/2506/2004 (Mal/04) and the IAV strain A/Puerto Rico/8/1934 (PR8)." (PMID 36309510, 2022). "Finally, quantifying lung viral titers after PR8 infection also showed a small reduction in titer in B3GAT1-transduced mice." (PMID 36309510, 2022). "Strikingly, B3GAT1 overexpression significantly reduced infection by all tested influenza viruses." (PMID 36309510, 2022). "Finally, to verify that EV-D68 infection was blocked at the binding and entry stage, we transfected genomic RNA and did not detect an observable difference in levels of viral replication in mCherry- and B3GAT1-overexpressing cells." (PMID 36309510, 2022). "As a first test of the potential of B3GAT1 expression as an antiviral strategy in vivo, we infected mice with Mal/04 (a mouse-adapted IBV) and found that exogenous B3GAT1 expression in the respiratory tract greatly improved infection outcome." (PMID 36309510, 2022).
B3GAT1 also shares sentences with these, for which no sentence is quoted: cancer (76 papers); COVID-19 (44); HCMV infection (44); autoimmune disease (22); HIV-1 infection (22); melanoma (16); co-infection (12); T-LGL leukemia (12); breast carcinoma (11); leukemia (11); Autoimmunity (10); colorectal cancer (9); immune dysfunction (9); gastric cancer (8); glioblastoma (8); rheumatoid arthritis (8); Ewing sarcoma (7); immune deficiency (7); neuroblastoma (7); Wilms tumor (7); AIDS (6); diabetes (6); Hypertension (6); latent infection (6); lung carcinoma (6); Lyme disease (6); acute myocardial infarction (5); glioma (5); head and neck cancer (5); infectious disease (5).
A further 229 diseases each share a sentence with B3GAT1 in 5 papers or fewer.